MIR3621 (microRNA 3621)
Synonyms: hsa-mir-3621
Gene: MicroRNA gene on chromosome 9 (137,169,186 to 137,169,270, reverse strand). Ensembl gene ENSG00000263697.
Homologues: Orthologues: chimpanzee MIR3621 (100% identical).